IL1B (interleukin 1 beta)
Diseases named in the same sentence as IL1B in open-access papers (continued):
Sharing a sentence is not in itself a finding about the gene and the disease.
infection (continued). "The loss of Dectin-1 reduced the levels of multiple proinflammatory cytokines in the lung tissue and serum of Abx-treated mice after nasal drip infection with K. pneumoniae, especially IL-1β." (PMID 40817809, 2025). "Assessing the differences in expression of the target genes between the time points, significant differences in expression were only observed for il1b and il6 between 6 and 18 h post infection for both treatments." (PMID 40517265, 2025). "Inflammatory cytokines including TNF‐α, IL‐15, IL‐23, and IL‐1β play a crucial role in the immune response to infections." (PMID 40539722, 2025). "The qPCR further highlighted that inflammatory cytokines such as IL-1β or IL-17a are expressed at the highest levels during early infection at day 1, as expected." (PMID 40586608, 2025). "TNF and IL1B, two key genes identified in the study, were selected for validation of their differential expression levels between the infection and control groups using qRT-PCR." (PMID 40725488, 2025). "As 20% of the participants reported resolution of symptoms 4–12 weeks after infection, the trends of IL–1β, IL–6, and TNF levels in these patients over time were also assessed." (PMID 40217938, 2025). "SARS-CoV-2 spike protein at 12 μg/ml concentration showed strong induction of IL-1β release in infection group (around fourfold) when compared with vaccination group." (PMID 40329195, 2025). "After 14 days of infection, IL-1β, IL-6, and LITAF were significantly increased in the H9 group compared with the other groups (p < 0.05)." (PMID 40218416, 2025). "We previously published, using a smaller cohort 5–24 months post infection, that there was a significant increase in IL-1β between HC and Cov, and between HC and nLongC." (PMID 41369364, 2025). "Compared to the GPS infection group, the expression of IL-6 in the 25 μg/mL baicalin group was significantly lower (p < 0.05), while the expressions of IL-1β and TNF-α were insignificantly lower (p > 0.05)." (PMID 40867785, 2025). "It is required to prevent the systemic spread of GAS, but once invasive infection is established, high levels of IL-1β correlate with increased disease severity." (PMID 39688411, 2025). "This is consistent with prior bulk RNA-seq analysis of foot tissue from CHIKV-infected mice at day 30 post infection that also detected an ongoing inflammatory response including elevated Ifng, Il1b, Tnf, Nlrp3, numerous chemokines, and immunoproteasome genes." (PMID 40678223, 2025). "In contrast, we found that S. aureus induced increased intracellular levels of the immature form of IL-1β (proIL-1β) in osteoclasts in accordance with the observed increase in IL-1β mRNA expression at 4 h following infection." (PMID 40056352, 2025). "During the blood infection stage, pro-inflammatory cytokines such as IL-1β, IL-6, IL-8, IL-12, IFN-γ, and TNF-α released by the host immune system play a decisive role in antimalarial immunity by regulating immune cell activation and pathogen clearance." (PMID 41422632, 2025). "We noted the increased expression of Il1b, iNos, Ifng in the case of H1N1wsn, and Il6 in the case of H1N1pdm09 infection." (PMID 41567998, 2025). "TNF-α, IL-1β, and IL-8 mRNA expression were significantly increased in the intestine after infection with A. hydrophila from grass carp." (PMID 40137743, 2025). "In our model, EV71 infection resulted in elevated levels of pro-IL-1β, cleaved IL-1β, and IL-18 in brain tissue, peaking on day 10 post-infection." (PMID 41288075, 2025). "When we looked at changes in analytes as a group over time after infection, the most dramatic change was in IL-1β." (PMID 41369364, 2025). "In the transcriptomic analysis of rabbits at 6 dpi with MPXV, pathways related to pathogenic infection and inflammatory response were enriched, and inflammatory genes such as IL1A, IL1B, and CXCL8 were significantly upregulated." (PMID 41157589, 2025).
infection (continued). "We report that neutrophils are recruited at the sites of infection and persist up to the death of the animal leading to an uncontrolled inflammation correlated with the expression of the pro-inflammatory cytokine IL1β." (PMID 39102417, 2024). "During the different time points (24 h, 48 h, and 7 days post-infection), a variation was detected for IL-6, IL-1β, considering the three different concentrations." (PMID 38399810, 2024). "One study found that infection with Trichinella pseudospiralis in EAE mice led to reduced levels of IL-1β, TNF, and IL-17 in both their spinal cord and splenocytes." (PMID 38250940, 2024). "In the context of SVV infection, the activation of the inflammasome and the direct cleavage of Pro-IL-1β by SVV 3C occur at the same time." (PMID 39038050, 2024). "Compared with the control group, the Pm challenge group showed significantly increased PARP1, HMGB1, IL-1β, and IL-18 protein expression in the blood vessels, indicating that Pm infection in mice triggered vascular inflammatory injury." (PMID 39850582, 2024). "These transcriptomic results are supported by the infection-induced secretion of IL1α, IL1β, IL8, and GM-CSF." (PMID 38902255, 2024). "In studies with respiratory disease-challenged animals, production of IL-6 and IL-1β in blood after ex vivo stimulation decreases after infection when compared to the same assay before the disease challenge." (PMID 38764468, 2024). "IL-1β and IL-6 are pro-inflammatory cytokines that are crucial for host-defense responses to infection and injury." (PMID 38464701, 2024). "Functionally, NKB cells have been described as expressing several cytokines, including IL-1b, IL-6, IL-12, and IL-15, upon stimulation/infection, in addition to their signature IL-18 secretion." (PMID 38739675, 2024). "During infection, the green fluorescence intensity of the Tg(il1β:GFP-F) increased at the site of virus replication before spreading to the connected tissues." (PMID 39102417, 2024). "In contrast to PCLS, no age-related differences were found in cytokines released by neutrophils and the cytokine response was generally low – only the very early pro-inflammatory cytokines IL-1β and TNFα were detectable 4 h after infection with P. aeruginosa." (PMID 38178102, 2024). "Several proinflammatory cytokines are secreted during the adaptive phase, such as TNF-α, IFN-γ, IL-1β, IL-12, and IL-18 which together form an inflammatory response regulating parasite growth and infection outcome." (PMID 38623843, 2024). "Although both Interferon-γ (IFNG) and IL-1B were up-regulated with direct RRV infection of MM chondrocytes, the inclusion of FLS altered their expression." (PMID 39028255, 2024). "During infection with the L. europaeus/GI.1 genotype, we noted a similar increase in the expression level of IL-1β and TNF-α, which was a 3.1-fold change (p = 0.045 for IL-1β and p = 0.004 for TNF-α)." (PMID 39273479, 2024). "In the case of macrophage infection by V. vulnificus and V. cholerae, the NLRP3 inflammasome senses the infection, leading to caspase-1 activation and IL-1β secretion." (PMID 39186780, 2024). "Infection of the cornea with ZIKV leads to the synthesis of the IL-1β, TNF-α, CCL5, and CXCL-10 which recruits other cells of the immune system to the cornea and this promotes inflammation and damage to corneal tissue leading to keratitis." (PMID 39795906, 2024). "It is suggested that the occurrence of ferroptosis in the early stage of infection can lead to the IL-1β production." (PMID 39353913, 2024). "Second, our findings imply that IL1β-mediated acute inflammation contributes to ongoing symptomatology and hyperinflammation many months after infection." (PMID 39008486, 2024). "Among the first responder cells, monocytes are significant producers of IL-1β during infection of gut epithelial cells by Toxoplasma or intestinal injury." (PMID 39221251, 2024).
infection (continued). "TNF-α, IL-1β and IL-6 are all pro-inflammatory cytokines, and they play complex roles in the inflammatory response, that can both help the host defend against infection and promote inflammation." (PMID 39176281, 2024). "Excessive production of pro-inflammatory cytokines, including IFN-γ, IL-1β, and IL-8, in the early stages of infection with virulent PRRSV strains is a major factor contributing to pulmonary damage." (PMID 40303049, 2024). "We found clear expression of IL-1β early during infection at 3 dpi, but these levels increased later; IL-1β reached its highest level in the cerebrum of hACE2-C57 mice before death, and no obvious increase in IL-1β was detected in the hamsters." (PMID 38256071, 2024). "This emphasizes the paramount significance of IL-1β, generated by monocytes/macrophages in the early stages of infection, in providing protection against excessive disease manifestation." (PMID 38590522, 2024). "It turns out that butyric acid derived from microbiota metabolism mediates increased resistance to infection in zebrafish through increased expression of IL-1β and an increase in the percentage of intestinal neutrophils." (PMID 38731838, 2024). "The fact that TNF-α elicits a rapid response at a critical time, such as the 10th day after infection, and that IL-1β follows in the subsequent days serves as a crucial determinant in neuroimmunopathogenesis." (PMID 39766497, 2024). "Knockdown of DARS2, but not related mt-aaRS in BEAS-2B cells significantly attenuated the release of the innate immune cytokines IL-1β, IL-6, and TNFα in response to infection with PA103." (PMID 39039092, 2024). "On a cell-to-cell basis, MPs secreted 47 times more mature IL-1β than neutrophils after infection with virulent Mtb H37Rv and 35 times more than that after BCG stimulation." (PMID 38803236, 2024). "The results showed that on the 12th day after infection, IL-1β and IL-6 were still highly expressed in the untreated group and the RBDA group, suggesting a strong inflammatory response because the wound was still infected." (PMID 38970013, 2024). "RSV infection also induced rapid and transient expression of Il1a, Il1b and Tnfa on day 1 post infection." (PMID 39127259, 2024). "IL-1β is synthesized by multiple immune cells in reaction to infection and injury to confer resistance against pathogens." (PMID 39598357, 2024). "In previous studies, HP-PRRSV BB0907 strain infection increased IL-1β, IL-6, TNF-α, and IFN-γ levels in the serum, and infection with the highly pathogenic PRRSV-1 Lena strain increased the serum levels of IFN-γ and IL-6." (PMID 39506759, 2024). "IL-1 (together with IL-1α and IL-1β genes) is the first interleukin identified from the IL-1 family (11 cytokines) engaged in the host immediate response to infections or inflammation." (PMID 38731114, 2024). "We show that IL-1β production in response to infection activates a cascade of events that results in damage to the structure of the commensal microbiota and release of oxygen into the colonic lumen." (PMID 38236896, 2024). "Pro-inflammatory cytokines such as TNF-α, IL-1β, IL-6, and IL-2 play several key roles in the brain, as follows: (i) They are crucial in initiating and regulating inflammation in response to infection, injury, or disease." (PMID 39337280, 2024). "Specifically, EVs from the ASC conditioned medium increased the bacterial control in treatment-naïve hMDMs and attenuated Mtb-induced IL-1β at 5 days post-infection." (PMID 39569198, 2024). "A significant downregulation of il1b was evident four hours post-infection as determined by RNA sequencing." (PMID 38590438, 2024). "We investigated the expression of IL-1β and IL-6 mRNAs in the early phase of infection at four and eight hpi with different C. jejuni strains." (PMID 38907359, 2024). "Remarkably, we found that IL-1β-/- mice were completely resistant to infection-induced mortality, while WT mice all succumbed to the infection." (PMID 38236896, 2024).
infection (continued). "It is a notable finding that the highest levels of IL-1β mRNA were observed on the 20th day following infection." (PMID 39766497, 2024). "After the piglets were challenged with PEDV, the IL-6 and IL-1β levels were significantly decreased in both the challenge and cohabitation infection groups with oral administration of the mutant strain S1/△Alr HLJ-27." (PMID 38430229, 2024). "MIS-C involves dysregulation of the innate immune system post-infection, activating the IL-1β pathway and increasing cytokine levels." (PMID 39149604, 2024). "While type-1 T-cells induce IL-6, IL-1β, TNF-α, and IL-12 production by monocytes/macrophages to fight the infection, type-2 T-cells are associated with a regulatory phenotype (IL-10 and TGF-β) and successful infection establishment." (PMID 39192975, 2024). "In this study, we observed that TNF-α increased from day 10 post-infection and remained at high pathological levels, whereas IL-1β increased from day 20 to day 30 post-infection, which is a particularly intriguing finding." (PMID 39766497, 2024). "In vitro data similarly revealed that depletion of AIM2 or ASC in murine macrophage cell lines diminishes IL-1β release following infection with Mtb or Mycobacterium bovis." (PMID 39324136, 2024). "IL‐1β is a common inflammatory cytokine and is involved in local and systemic responses to injury, infection, and inflammation." (PMID 39119947, 2024). "Overall, these comparisons suggest that both Ad-HA/NP+Ad-IL-1β immunization and pH1N1 infection invoke a greater immune response than Ad-HA/NP, resulting in greater differential gene expression." (PMID 39024231, 2024). "Using qPCR, we evaluated the expression of cytokines that are important for neutrophil recruitment to sites of infection, including IL1β, IL-6 and TNFα, as well as the neutrophil chemokines CXCL1 and CXCL2." (PMID 39509414, 2024). "As seen after LPS alone, expression of Il1a, Il1b and Tnfa increased 12 h after LPS exposure but declined during the first 2 days of infection." (PMID 39127259, 2024). "Levels of pro-inflammatory cytokines IL-1β and IL-6 were reduced in the hypothermia group at 6 h post-infection." (PMID 38951957, 2024). "IL‐1β is a known inflammatory cytokine and is involved in local and systemic responses to injury, infection, and inflammation." (PMID 39119947, 2024). "We found that IL-1β-/- mice infected intravenously with a low dose of Salmonella die from the infection in a similar manner as WT mice." (PMID 38236896, 2024). "A lower increase in IL-1β was also detected at the highest concentration of the two M. bovis spoligotypes one week post-infection." (PMID 38399810, 2024). "In peritoneal macrophages upon SIRT1 (EX-527-1 μM) or SIRT3 (3-TYP-1μM) chemical inhibitor treatment, an increase in IL-6 and IL-1β cytokine levels was observed at 6 hr post-infection." (PMID 39693143, 2024). "ATF3 has been reported to facilitate the generation of IL-17A in γδ T cells through macrophage-mediated secretion of IL-1β, thus modulating the response to infection." (PMID 38255898, 2024). "IL-1β are produced by immune cells in a variety of different infections in animals or humans, primarily induced by LPS." (PMID 38997981, 2024). "mRNA levels of Il1β, Tnf and Il18 were significantly increased in the acute phase of the infection compared to those in uninfected salivary gland tissue." (PMID 39355243, 2024). "The protective effect of cytokines in the axis IL-12/IFN-γ/TNF-α and IL-1β to control the infection is evident." (PMID 39062562, 2024). "Interleukins are the most important cytokines released during infection, which include IL-1β, IL-18, IL-6, IL-12, and IL-17." (PMID 39042701, 2024). "A functional difference between IL-1α and IL-1β has been reported for several infections, including group A Streptococcus39 and Toxoplasma gondii." (PMID 38382577, 2024).
infection (continued). "As an inflammatory factor, IL-1β can promote the growth and differentiation of B lymphocytes, being conducive to the formation of antibodies and improving the anti-infection effects of the body." (PMID 39109341, 2024). "In particular, the TNF-α, IL-1β, and IL-6 levels increased by around 18-, 11-, and 13-fold, respectively, at 24 h post-infection and by around 23-, 22-, and 21-fold, respectively, at 48 h post-infection compared to uninfected PAMs." (PMID 38664855, 2024). "In the liver the relative level of mRNA expression of IL-1β was decreased during infection with L. europaeus of both genotypes (3.6-fold reduction for genotype GI.1 (p = 0.002) and 3.1-fold reduction for GI.2 (p = 0.004)) compared to the control group." (PMID 39273479, 2024). "Considering gene expression patterns in the pituitary gland, il1β expression was higher in fish fed TRP than in those fed CTRL at 4 h post-infection." (PMID 38548769, 2024). "We measured TNF-α, IL-1β, and IL-6 to confirm the immune system’s activation and the level of infection within the body." (PMID 39066795, 2024). "HuN2021 infection was accompanied by the upregulation of proinflammatory cytokines, such as IL-6, IL-1β, IL-8, TNF-α, and CCL8, as well as the immunomodulatory cytokines IL-10 and IFN-γ, at the mRNA and protein levels." (PMID 39506759, 2024). "Numerous proinflammatory cytokines exhibited decreased expression in Omicron-infected BSs compared to those infected with the WT virus, including IL6, CXCL1, CXCL2, and IL1B, which play a crucial role in attracting immune cells to infection sites." (PMID 38741604, 2024). "Despite a reduction in the IL-1β mRNA levels on post-infection day 30, these remained elevated in comparison to the healthy control groups." (PMID 39766497, 2024). "Post-infection, excessive production of inflammatory mediators such as IL-1β, IL-6, IL-8, TNF-α, MCP-1, and IP-10, as well as the presence of endothelial inflammation markers (IL-6, TNF-α, ICAM-1) in lung tissues, have also been reported." (PMID 38600563, 2024). "We found that Salmonella levels were reduced 100-fold in the cecal lumen of IL-1β-/- mice 4 days post-infection (d.p.i.)compared to WT mice." (PMID 38236896, 2024). "Cas-1 cleaves pro-IL-1β at an aspartic acid site, resulting in a mature proinflammatory cytokine IL-1β, central to the cell’s response to infection." (PMID 38791515, 2024). "In this study, coumarin derivative supplementation in C. rodentium-infected mice downregulated the cytokine genes for IL-6 and IL-1b, which were increased by infection in colonic tissues." (PMID 39081865, 2024). "This suggests that IL-1β has a protective role during the later stage of infection and is possibly why RSV has evolved proteins to suppress it." (PMID 38382577, 2024). "The protein levels of TNF-α, MCP-1 and IL-1β upon the treatment with rHtrA for 24 h equalled those of the uninfected controls, whereas the level of IL-8 was significantly decreased by rHtrA infection compared to the control." (PMID 39035711, 2024). "Surprisingly, the results showed that only IL-1β and IL-18 levels were significantly higher in cells infected with B. pseudomallei than those infected with B. thailandensis at 3 and 6 h post-infection." (PMID 39042701, 2024). "As illustrated with our results, the levels of IL-6, IL-8 and IL-1β gradually increased with the duration of CV-A10 infection." (PMID 38641810, 2024). "IL-1β, a potent pro-inflammatory cytokine involved in host defense against infection and injuries, was also detected after stimulation." (PMID 39457035, 2024). "Both compounds also reduced IL-1β levels at 48 h post-infection by around 49% and 78%, respectively, and the results were statistically similar in this case." (PMID 38664855, 2024). "A previous study reported that infection of murine dendritic cells with attenuated strains rMP-12 or RVFV deleted of NSs can trigger IL-1β release into the supernatant in the NLRP3-dependent manner only with LPS priming." (PMID 39213434, 2024).